IGF1 (insulin like growth factor 1)
Diseases named in the same sentence as IGF1 in open-access papers (continued):
Sharing a sentence is not in itself a finding about the gene and the disease.
cervical cancer (continued). "Increased levels of IGF-1 in patients with T2DM and overexpression of IGF-1R in cervical cancer cells might activate the IGF intracellular signaling pathway, resulting in a poor prognosis." (PMID 38392069, 2024). "The authors proposed a mechanism for the action of LncCCLM in cervical cancer, according to which cytoplasmic LncCCLM interacts with Staufen double-stranded RNA binding protein 1 (STAU1) to promote the decay of the insulin-like growth factor 1 (IGF-1) mRNA." (PMID 37407839, 2023). "In addition, IGF-1 and KCC colocalize in the surgical specimens of cervical cancer, suggesting the possible autocrine or paracrine effect of IGF-1 on KCC production in vivo." (PMID 35008759, 2021). "IGF-1 and EGF were shown to stimulate the recruitment of KCC4 from a presumably inactive cytoplasmic pool of endoplasmic reticulum (ER) and Golgi to the front-end plasma membrane of migrating cervical cancer cells." (PMID 35008759, 2021). "We showed that four miRNAs (miR-502, miR-145, miR-142, and miR-33b) are independent and common prognostic biomarkers for patients with cervical cancer, and seven proteins (CXCL12, IGF1, PTPRC CDH5, RAD51B, REV3L, and WDHD1) are key genes significantly related to lymph node metastasis." (PMID 32457603, 2020). "The comparative analysis of study groups versus the control group based on the Mann-Whitney U test revealed statistically significant differences in the concentrations of IGF-1 in the group of patients with H-SIL (P=0.047) and cervical cancer compared with controls." (PMID 25384883, 2015). "On the other hand, the results from another study of preoperative serum total IGF-1 or IGFBP-3 levels failed to predict cervical cancer mortality and recurrence." (PMID 25333772, 2014). "Epidermal Growth Factor (EGF), Insulin Growth Factor 1 (IGF-1) and Vascular Endothelial Growth Factor (VEGF) are known to regulate cervical cancer cell proliferation and invasiveness which play key roles in determining the high-risk factors and lead to recurrence and mortality." (PMID 25070070, 2014). "The growth and invasiveness of cervical cancer cells were dose-dependently stimulated by IGF-1, whereas those of normal cervical epithelial cells were not." (PMID 18781172, 2008). "(ii) Preoperative serum total IGF-1 or IGFBP-3 levels failed to predict cervical cancer death and recurrence." (PMID 18781172, 2008). "In that report, we also showed that IGF-1 induces depalmitoylation and repalmitoylation, a dynamic palmitoylation turnover, of the PM-targeted Flot-1, which facilitates prolonged activation of IGF-1R on the cell surface and hence promotes cervical cancer cell proliferation." (PMID 30631151, 2019). "Moreover, the serum level of IGF-1 or IGFBP-3 did not statistically differ between the two distinct IGF-1R overexpressions (P=0.77 and P=0.07, respectively), indicating no direct correlation between circulating IGF-1 or IGFBP-3, and IGF-1R overexpression in cervical cancer cells." (PMID 18781172, 2008).
diabetic retinopathy (39 papers, 2003 to 2026). "Dysregulation of IGF-1 signaling has been implicated in several retinal diseases, such as diabetic retinopathy and age-related macular degeneration." (PMID 40733109, 2025). "Previous studies have found that polymorphisms in the IGF-1 gene are associated with conditions such as breast cancer, gastric cancer, coronary artery disease, childhood IgA nephritis, diabetic retinopathy, AMD and high-grade myopia." (PMID 38300646, 2024). "Neovascularization is the final common pathway of diabetic retinopathy, and IGF-1 has been associated with retinal neovascularization." (PMID 35248150, 2022). "On the other hand, overexpression of IGF1 in the retina results in changes similar to those of diabetic retinopathy (pericyte loss, capillary basement membrane thickness, inner retinal microaneurysms, and neovessels)." (PMID 35611927, 2022). "This study aimed to explore the association of insulin-like growth factor 1 gene (IGF1) polymorphisms with diabetic retinopathy (DR) in a Chinese Han population." (PMID 29152139, 2017). "IGF-1 is associated with diabetic retinopathy, increased retinal vascular permeability, and retinal and choroidal neovascularization." (PMID 28835854, 2017). "Both insulin and IGF-1 have been implicated in the control of retinal endothelial cell growth, neovascularization and diabetic retinopathy." (PMID 26075045, 2015). "Therefore, we propose that glycated hemoglobin (HbA1c) is a main risk factor for retinopathy and serum IGF-1 influences the development of severe diabetic retinopathy." (PMID 35248150, 2022). "Ultimately, understanding the homeostatic role of IGF-1 in retinal cell survival and repair highlights its potential benefits in managing diabetic retinopathy." (PMID 40362202, 2025). "The evidence suggests that in the early stages of diabetic retinopathy, IGF-1 plays a direct role in regulating both VEGF levels and the disruption of the blood-retina barrier (BRB)." (PMID 38300646, 2024). "IGF-1 also has been reported to be a potent stimulator of retinal endothelial cell growth and to play a major role in the development of diabetic retinopathy." (PMID 39638246, 2024). "IGF-1 downregulation decreases the activation of AKT in diabetes retinopathy, which abrogates the neuroprotective effect, upregulates VEGF expression, and thus induces neovascularization." (PMID 39638246, 2024). "At baseline, systemic insulin-like growth factor-1 concentration was higher in the diabetic retinopathy group (57 pg/ml) than in the age-related macular degeneration group (35 pg/ml) (p=0.0056)." (PMID 34956670, 2021). "IGF-1 activity is reported to be negatively controlled by the action of PTP1B and inhibiting PTP1B is considered to have neuroprotective effects in diabetic retinopathy by modulating IGF-1 activity." (PMID 32760098, 2020). "This study although not fully representative of the general population suggests a possible ‘protective’ role of low IGF-1 in the development of diabetic retinopathy." (PMID 26075045, 2015). "Although IGF-1 was once thought to have the same effect as insulin, recently a relationship between IGF-1 and diabetic retinopathy has been suggested." (PMID 23326534, 2013). "Although the exact role of IGF-1 in the pathogenesis of diabetic retinopathy remains to be elucidated, it is possible thatIGF-1 can be modulated by oxidative stress via PKC pathway." (PMID 17641741, 2007). "This may trigger an acute imbalance of growth factors like vascular endothelial growth factor and IGF-1, accelerating neovascularization and diabetic retinopathy progression." (PMID 41560719, 2026). "This reversal may be attributed to the synergistic collaboration of IGF-1 with dopamine in mitigating diabetic retinopathy by downregulating VEGF." (PMID 38300646, 2024). "Moreover, inhibiting abnormal IGF-1 signaling in the retina has been demonstrated to prevent and reverse diabetic retinopathy in male rats." (PMID 38300646, 2024).
diabetic retinopathy (continued). "Our results support the idea that IGF1 in diabetic retinopathy or retinopathy of prematurity may be derived from retinal microglia." (PMID 35611927, 2022). "Investigating other potential pathways such as IGF-1-, integrin-, or growth factor-mediated signaling (predicted from targetscan.org) can be investigated to continue to increase understanding of the role of miR-15b/16 in diabetic retinopathy." (PMID 25888955, 2015). "Nevertheless, while experimental and clinical evidence suggests that serum IGF-1 concentrations may be involved in the development of diabetic retinopathy the relationship is still controversial." (PMID 26075045, 2015). "In addition to VEGF, the development of diabetic retinopathy has been linked to the deregulation of other growth factors such as TGF-β, IGF-1, and bFGF." (PMID 23251343, 2012). "Regarding the GLP1-ra pharmacodynamics, a hypothesised mechanism through which GLP1-ra predisposes to diabetic retinopathy is via rapid reduction in HbA1c which can lead to alterations in VEGF and IGF-1 that can lead to the development or early worsening of diabetic retinopathy." (PMID 38584180, 2024). "Therefore, IGFBP2 may influence neovascularization in diabetic retinopathy through modulating VEGF activity mediated by IGF1." (PMID 38124748, 2023). "Even though IGF-1 may play a pathogenic role in diabetic retinopathy, most research has failed to provide any convincing data regarding the relationship between IGF-1 and the development of retinopathy." (PMID 35248150, 2022). "This study provides evidence that IGF‐1 might be a key factor in the paracrine action of T2DM‐BMMSCs on endothelial cell behaviour, thus contributing to the pathogenesis of microvascular complications associated with the diabetic condition, including diabetic retinopathy." (PMID 27641937, 2017). "The goal of this study was to characterize the effects of IGFBP-3 actions on REC-monocyte adhesion relevant in the progression of diabetic retinopathy, independent of any IGF-1 response." (PMID 23592916, 2013). "This response is IGF-1- and calcium-independent, but requires PI3K/Akt activation, suggesting that IGFBP-3 has novel protective effects on retinal and systemic vasculature and may be a therapeutic candidate for ocular complications such as diabetic retinopathy." (PMID 22792172, 2012).
hyperprolactinemia (39 papers, 2008 to 2026). Abnormally high level of prolactin in the blood. "Immediately postoperatively, thyrotoxicosis and hyperprolactinemia resolved, IGF-1 levels declined, acromegalic features improved, and menses resumed." (PMID 42256640, 2026). "In six of these 53 patients with IGF-1 normalization (11.3%), hyperprolactinemia persisted in the postoperative period, with median levels of 38.4 (range 24–68) ng/dL." (PMID 40590355, 2025). "In our study, there were 10% of the cases classified as cured based on serum IGF-1 levels that had persistent hyperprolactinemia." (PMID 40590355, 2025). "Biochemical investigations revealed elevated IGF-1 [588 ng/ml, reference range (RR) 100–242], markedly elevated basal growth hormone (>80 ng/ml; RR, 0.12–9.88), and hyperprolactinemia in the tumoral range (832 ng/ml; RR, 5–25)." (PMID 39449742, 2024). "Biochemically there was an elevated IGF-1 (1167μg/l) and a discrete hyperprolactinaemia (25,19 ng/mL)." (PMID 36157469, 2022). "The pathophysiology of gigantomastia is still unknow; although no precise mechanism is known for this rare clinical entity, theories such as end-organ hyper-sensitivity, autoimmune stimulation antibodies, high IGF-1 and hyperprolactinemia have been proposed." (PMID 28904695, 2017). "PRL seems to be markedly increased in serum along aging (hyperprolactinemia), GH secretion declines during normal aging, resulting in lower serum levels of IGF1, and very disparate results have been reported with regard to Igbp-1." (PMID 23301049, 2013). "Breast changes in systemic lupus are related to estrogen hyperstimulation, hyperprolactinaemia, and elevated IGF1." (PMID 22924044, 2012). "Moreover, total Ghr knockout induces hyperprolactinemia and affects gonadal functions in male mice, likely through GH resistance and a reduction in peripheral IGF-1 levels." (PMID 39623508, 2024). "He had hyperprolactinemia and IGF-1 higher than the normal reference range for age." (PMID 36967793, 2023). "Dopamine receptor agonists are useful in cases with associated hyperprolactinemia or as an adjunct therapy to SSAs in cases with lack of biochemical control and IGF-1 levels up to 1.5 times above the normal range." (PMID 31365626, 2019). "Laboratory evaluations revealed a massive hyperprolactinemia of 5475 mU/L (normal range < 500 mU/L), high growth hormone levels (that is, 43.2 mU/mL at 8 a.m.), and an elevated insulin-like growth factor 1 (IGF-1) of 892 ng/mL (age-related normal range, 111 ng/mL to 693 ng/mL)." (PMID 22273876, 2012). "Biochemical evaluation revealed central hyperthyroidism with elevated free T4 and inappropriately normal TSH, markedly elevated insulin-like growth factor 1 (IGF-1) and GH, hyperprolactinemia, and elevated α-subunit." (PMID 42256640, 2026). "At diagnosis, the median fasting GH concentration was 11.9 μg/L (IQR: 4.3 - 26.0), the mean IGF-1 concentration was 3.4 x ULN ± 1.2 and approximately 31% of patients had hyperprolactinemia." (PMID 36187106, 2022). "Relevant laboratory values were notable for mild hyperprolactinemia (felt to be due to stalk effect and not primary production from the tumor), severe hypogonadotropic hypogonadism, mild central hypothyroidism, and low insulin-like growth factor-1 indicative of growth hormone deficiency." (PMID 34549183, 2021). "High IGF1 and GH (nadir in OGTT—oral glucose tolerance test) levels at diagnosis were detected in 11 cases, with a mean value of 3.47 ± 1.56 (×ULN—upper normal limit), where 3 cases had hyperprolactinemia and 2 cases presented with mixed PRL- and GH-secretion." (PMID 38248047, 2024). "Both groups were comparable with respect to age, reasons for hyperprolactinemia, smoking, BMI, blood pressure, HOMA1-IR, and plasma levels of glucose, total prolactin, monomeric prolactin, macroprolactin, FSH, SHBG, thyrotropin, ACTH and IGF-1." (PMID 37685540, 2023).
hyperprolactinemia (continued). "Patients with mildly increased levels of GH and IGF-1, with or without hyperprolactinemia, are more likely to have benefited from cabergoline treatment." (PMID 35612842, 2022). "In patients with hyperprolactinaemia, metformin reduced plasma levels of prolactin, but did not affect circulating levels of thyrotropin and IGF-1." (PMID 25239203, 2015). "There were no between-group differences in age, smoking habits, reasons for hyperprolactinemia, the body mass index, blood pressure, glucose, HOMA1-IR, thyrotropin, free thyroid hormones, total prolactin, monomeric prolactin, macroprolactin, FSH, LH, ACTH and IGF-1." (PMID 37297964, 2023). "Neither the presence of hyperprolactinemia nor the positive immunohistochemical staining for prolactin was related to the reduction in IGF-1 or the rate of disease control, supposing that presence of PRL expression might not predict the response." (PMID 35612842, 2022). "The meta-analysis showed that the response to cabergoline is dependent on the IGF-1 baseline levels, with greater chances to achieve IGF-1 levels normalization with lower basal IGF-1 levels, and not on the presence or absence of hyperprolactinemia." (PMID 31766255, 2019).
Impaired glucose tolerance (37 papers, 2005 to 2025). An abnormal resistance to glucose, i.e., a reduction in the ability to maintain glucose levels in the blood stream within normal limits following oral or intravenous administration of glucose. "Additionally, perturbations in IGF-1 levels are linked to impaired glucose tolerance and susceptibility to T2D, emphasizing the importance of maintaining IGF-1 homeostasis within the brain." (PMID 38916735, 2024). "This elevation suggested systemic atherosclerosis linked to impaired glucose tolerance.S1–3 On the other hand, serum expression of TNFRSF1A, CXCL4, MIP‐1 γ, MMP‐3, VEGFR2, IGF‐1, HGFR, OPN, and OPG was significantly lower in db/db mice." (PMID 39001701, 2024). "Lastly, impaired glucose tolerance, IR, and resistance to IGF1 can be observed in mice with defect in IRS1 gene." (PMID 39420901, 2024). "Low levels of IGF-1 can predict impaired glucose tolerance, T2DM, and cardiovascular disease." (PMID 35094288, 2022).
retinopathy of prematurity (36 papers, 2012 to 2026). A bilateral retinopathy characterized by neovascularization, scarring, retinal detachment, and eventually blindness. "ROP predictive models use postnatal growth as an alternate estimation for low IGF-1 levels to assess the risk of retinopathy of prematurity." (PMID 39942424, 2025). "Low IGF-1 serum levels in preterm newborns are linked to slower head circumference growth and are directly correlated with the extent of retinopathy of prematurity." (PMID 38618439, 2024). "It has been reported that long-term low serum IGF-1 levels from birth are associated with postnatal growth restriction, brain developmental disorders, retinopathy of prematurity (ROP), and chronic lung disease." (PMID 35407507, 2022). "Low levels of IGF-1 have been associated with different complications in premature infants including retinopathy of prematurity (ROP) and bronchopulmonary dysplasia (BPD)." (PMID 32655560, 2020). "WINROP (weight, insulin-like growth factor 1 (IGF-1), neonatal retinopathy of prematurity risk algorithm) established that early weight gain and IGF-1 levels, primarily in the first 4 weeks of life, predict which infants will develop vision-threatening retinopathy of prematurity." (PMID 31892145, 2019). "Adiponectin, an adipocytokine positively associated with growth in preterm infants, and IGF-1 have differential effects on the developing retina during the early vasoattenuative phase compared to the later neovascular phase of retinopathy of prematurity development." (PMID 31892145, 2019). "Moreover, in neonates born before term, low IGF-1 concentration is a causative factor for the development of retinopathy of prematurity (ROP)." (PMID 24311895, 2013). "Low postnatal levels of IGF-1 are associated with several complications of prematurity, including retinopathy of prematurity (ROP), bronchopulmonary dysplasia, and poor neurodevelopmental outcome at 2 years of age." (PMID 38427732, 2024). "IGF-1 in breast milk is thought to protect premature infants from retinopathy of prematurity (ROP) in the first 6 weeks of life; IGF-1 deficiency during the first weeks of neonatal life was associated with ROP." (PMID 31174304, 2019). "Weight, insulin-like growth factor-1, retinopathy of prematurity's suboptimal performance in this Brazilian sample highlights the need for country-specific algorithm adjustments." (PMID 39879412, 2025). "WINROP (weight, insulin-like growth factor 1, neonatal, retinopathy of prematurity) is an online surveillance system based on gestational age, birth weight and weekly weight gain that can predict infants at risk of sight-threatening retinopathy of prematurity." (PMID 38310200, 2024). "According to this, the WINROP tool (weight, insulin-like growth factor I, neonatal, retinopathy of prematurity) based on neonatal growth and measurements of levels of insulin-like growth factor-1 (IGF-1) has recently been developed as a prognostic marker." (PMID 28830469, 2017). "The mechanism that may link PGF with such morbidities as bronchopulmonary dysplasia or retinopathy of prematurity could be a low level of insulin-like growth factor-1 (IGF-I)." (PMID 39942424, 2025). "Early aggresive parenteral nutrition with AAs and lipids is associated with higher levels of IGF-1 and IGFBP-3 which might decrease the risk of retinopathy of prematurity." (PMID 33489343, 2020). "Fat mass, fat-free mass, and percent body fat are differentially associated with adiponectin, IGF-1, and IGFBP3, so changes in these variables during the neovascular phase may alter retinopathy of prematurity risk." (PMID 31892145, 2019). "The computerized clinical algorithm Weight, Insulin-like growth factor (IGF-1), Neonatal Retinopathy of Prematurity (WINROP) has been developed as a non-invasive tool for identifying infants at risk for ROP based on postnatal weight gain and IGF-I levels." (PMID 32024231, 2020).
retinopathy of prematurity (continued). "In preterm, retinopathy of prematurity (ROP) is a common complication that is characterized by retinal blood vessel growth arrest and retinal vascular growth disorganize caused by a large number of growth factors such as VEGF and IGF-1." (PMID 33313310, 2020). "In the mouse model of retinopathy of prematurity, exogenous IGFBP3 promoted vessel survival during the vaso-obliterative hyperoxic phase and increased vessel regrowth during the relative hypoxic phase independent of IGF-1, and reduced apoptosis in retinal neurons." (PMID 23878504, 2013).